RNU6-235P (RNA, U6 small nuclear 235, pseudogene)
Gene: Small nuclear RNA gene on chromosome 3 (38,303,773 to 38,303,879, reverse strand). Ensembl gene ENSG00000199514.
Homologues: Orthologues: chimpanzee U6 (99% identical), macaque U6 (94% identical), dog U6 (79% identical), rabbit U6 (73% identical), pig U6 (72% identical), rabbit U6 (72% identical). Paralogues in human: RNU6-11P (91% identical), RNU6-37P (91% identical), RNU6-480P (91% identical), RNU6-774P (91% identical), RNU6-21P (90% identical), RNU6-86P (90% identical), RNU6-87P (90% identical), RNU6-1 (89% identical), RNU6-144P (89% identical), RNU6-16P (89% identical), RNU6-2 (89% identical), RNU6-3P (89% identical), and 1289 more.